MYC (MYC proto-oncogene, bHLH transcription factor)
Diseases named in the same sentence as MYC in open-access papers (continued):
Sharing a sentence is not in itself a finding about the gene and the disease.
non-small cell lung carcinoma (135 papers, 2009 to 2026). A group of at least three distinct histological types of lung cancer, including non-small cell squamous cell carcinoma, adenocarcinoma, and large cell carcinoma. "The drug sensitivity to PF06939999 in non-small cell lung cancer (NSCLC) is associated with signaling pathways involving MYC, cell cycles, and spliceosomes and with mutations in splicing factors." (PMID 38136401, 2023). "Further studies are necessary to clarify the role of KRAS mutations and MYC amplifications in MET-altered non-small-cell lung cancer." (PMID 30459450, 2019). "MYC is a key oncogenic driver frequently overexpressed in non-small cell lung carcinoma (NSCLC) and other cancers, where its protein levels often exceed what would be expected from MYC mRNA levels alone, suggesting post-transcriptional regulation." (PMID 40943063, 2025). "JQ1 suppresses expression of CD47 and PD-L1 in acute lymphoblastic leukemia, melanoma, and non-small cell lung cancer (NSCLC) cells through a c-MYC-mediated pathway." (PMID 39318624, 2024). "A new study has revealed that THZ1 enhances anti-PD-1 therapy efficacy via the c-MYC-mediated signaling pathway in non-small cell lung cancer." (PMID 33889549, 2021). "In non-small cell lung cancer, Hu and Lu found c-MYC activated BCYRN1 to promote tumor cell metastasis through up-regulating MMP-9 and MMP-13." (PMID 31652309, 2019). "Low dose erlotinib-cisplatin combination exhibits its anti-tumor activity by targeting angiogenesis through modulation of c-MYC/HIF-1α/VEGF pathway in non-small cell lung cancer cells with EGFR exon 19 deletions." (PMID 30619741, 2018). "C646 caused suppression of MYC expression and apoptosis in CBP-deficient cancer types, specifically in CBP-mutant non-small cell lung cancer, T-ALL, and follicular B-cell lymphoma." (PMID 28505071, 2017). "Hu and Lu found BCYRN1 up-regulated in non-small-cell lung cancer (NSCLC) in a MYC dependent manner and to be involved in cell migration and invasion." (PMID 28704924, 2017). "In the non-small cell lung cancer cell line H1299, depletion of MYC via shRNA led to a decrease in POLRMT protein." (PMID 27590350, 2016). "Data matrices were generated by measuring anti-proliferative effects (IC50) of i-CDK9 and JQ1 as a single agent or in combination on both HeLa and H1792, a non-small cell lung cancer cell line with significant MYC amplification (CN = 8)." (PMID 26083714, 2015). "Recent studies showed that conditional gene silencing of WRN expression in non-small-cell lung cancer xenografts that are over-expressed with c-MYC inhibits tumor growth, suggesting that targeting WRN protein inhibits growth of c-MYC-associated cancers." (PMID 25620975, 2014). "We have examined c-MYC for its ability to induce metastasis in a C-RAF-driven mouse model for non-small-cell lung cancer." (PMID 19551151, 2009). "Topper and colleagues had demonstrated that depletion of MYC could reversed immune evasion in mouse, which in turn achieved the purpose of treating non-small cell lung cancer, corresponding clinical trial is still ongoing." (PMID 33738257, 2021). "In addition, PUS1 may participate in DNA repair, E2F targeting, MYC targeting, and the G2M checkpoint and promote malignant transformation in non-small cell lung cancer (NSCLC) through mcm5 or XPO1." (PMID 41501031, 2026). "In a model of non-small cell lung carcinoma (NSCLC), c-MYC switched off the onset of autophagy via the induction of miR-150, leading to increased ER stress, DNA damage, and cancer cell proliferation." (PMID 37111592, 2023). "In non-small cell lung cancer (NSCLC), H3K18la activates the transcription of POM121, promoting the binding of MYC to the PD-L1 promoter." (PMID 40050608, 2025).
non-small cell lung carcinoma (continued). "In non-small cell lung cancer (NSCLC), H3K18 lactylation promotes immune suppression by inducing pore membrane protein 121 (POM121), which increases MYC activity and programmed cell death-ligand 1 (PD-L1) expression." (PMID 40057816, 2025). "Another study revealed that HIF1A-As2 epigenetically activates MYC by attracting DHX9 to the MYC promoter, thereby promoting the transcription of MYC and its target genes in KRAS-driven non-small cell lung cancer." (PMID 39668816, 2024). "In non-small cell lung cancer, miR-342-3p has been suggested to play a tumor-suppressive role by negatively regulating RAP2B (a member of the RAS oncogene family) and MYC transcriptional activity by targeting E2F1 (a MYC-cooperating molecule)." (PMID 28035073, 2017). "We have recently demonstrated that aberrant PI3K signalling in Non-Small Cell Lung Cancer cells induces the mRNA expression of oncogenic transcription factors (HMGA1, JUN-B, FOS and MYC)." (PMID 23408974, 2013). "In male non-small cell lung cancer cells, linc-SPRY3-2/3/4 has been found to interact with IGF2BP3, resulting in a decrease in the stability of specific IGF2BP3 binding mRNAs like anti-apoptotic HMGA2 mRNA and oncogenic c-MYC mRNA." (PMID 38760723, 2024). "While MYC-amplified tumors may be more sensitive to translation inhibition, RAS-driven cancers such as PDAC and non-small cell lung cancer also depend on MYC52,79, making them promising indications for such a therapeutic approach." (PMID 37673892, 2023). "In non-small-cell lung cancer (NSCLC), Baylin and colleagues showed that in vitro combinatorial treatment of HDACi and DNMTi resulted in the suppression of MYC signaling, as well as the induction of Type I IFN pathway related genes and antigen presentation genes." (PMID 33403469, 2021). "Indeed, radiation can induce the formation of colocalized c-MYC and ƴ-H2AX foci in H1299 human non-small cell lung carcinoma cell lines derived from lymph nodes." (PMID 34063424, 2021). "This study aimed to evaluate the relationships between c-MYC and EZH2 immunohistochemical expression and survival in patients with small cell lung carcinoma (SCLC) and non-small cell lung carcinoma (NSCLC)." (PMID 41928013, 2026). "We designed this work to explore the role of a key oncogene, MYC, in the pathogenesis of LUAD, and this study aims to identify important long noncoding RNA (lncRNA)-microRNA (miRNA)- transcription factor (TF) interactions in non-small cell lung cancer (NSCLC) using a bioinformatics analysis." (PMID 33540574, 2021). "For example, the fifth ranked regulator MYC was recently proved to mitigate its oncogenic activity by chaperone-mediated autophagy (CMA) regulation and the ninth ranked regulator XIST was determined to increase autophagy activity in non-small-cell lung cancer by regulation of ATG7." (PMID 30400235, 2018). "Specifically, JQ1 did not alter MYC transcription in embryonic stem cells (ESCs) or in non-small cell lung carcinoma (NSCLC) harboring alteration in KRAS." (PMID 26111384, 2015).
breast tumors (129 papers, 2004 to 2026). "CREBBP, EP300, ESR1, GATA3, and MYC are well-known genetic biomarkers and mutate frequently in breast tumors." (PMID 34235216, 2021). "Upregulation of c-MYC and its downstream effectors is associated with poor disease outcome, high metastatic capacity, and endocrine resistance in breast tumors." (PMID 33808259, 2021). "MYC overexpression and amplification are associated with breast tumor progression and increased risk of relapse and death." (PMID 30728358, 2019). "About 40-45 % of all breast tumors exhibit MYC overexpression, which is associated with unfavorable prognostic markers." (PMID 27590516, 2016). "Activation of MYC has been linked to acquired antiestrogen resistance in human breast tumors and poor clinical outcome." (PMID 25339305, 2014). "The selection of the oncogenome during mouse and human breast tumor development is markedly different, apart from the MYC gain and RB1-associated loss." (PMID 20735817, 2010). "Studies demonstrated a subset of breast tumors induced by MYC overexpression that fail to undergo sustained regression upon MYC inactivation have mutations in K-Ras." (PMID 18461184, 2008). "MYC overexpression is associated with poor prognosis in breast tumors (BCa)." (PMID 29523126, 2018). "From these results, we speculated that K-Ras may be mutated in MYC-induced lung tumors, as has been observed in MYC-induced breast tumors." (PMID 18461184, 2008). "In tumor cells, UBR5 fine-tunes MYC protein levels, balancing cell growth and survival, thus contributing to therapeutic resistance by protecting breast tumors from MYC-mediated apoptosis-priming." (PMID 39857943, 2025). "This research investigated the repercussions of miR-32-5p suppression, in the MCF-7 cells of breast neoplasm, on c-MYC expression." (PMID 40711670, 2025). "Clinical evidence indicates that c-MYC is frequently overexpressed in breast tumors and contributes to both oncogenic transformation and tumor maintenance." (PMID 40710353, 2025). "This study is the first to demonstrate a plausible regulatory relationship between miR-32-5p and c-MYC in breast tumor cells." (PMID 40711670, 2025). "Based on these findings, we postulate that mG3 breast tumors are highly proliferative, and that their proliferation is stimulated through mTOR and c-MYC signaling." (PMID 40740860, 2025). "SLC1A5 protein was significantly expressed in breast tumours with high Ki67 (P < 0.001) and MYC (P = 0.02) expression." (PMID 39843491, 2025). "T. gondii transcriptionally regulates several signaling pathways by altering the hub genes such as BRCA1, MYC and IL-6, which can inhibit the breast tumor growth and migration, hinting at a potential therapeutic strategy." (PMID 38654350, 2024). "The expression of the PVT1 gene correlated with MYC expression in human breast tumors according to Pearson correlation analysis of data obtained from 4307 patients." (PMID 38556549, 2024). "GSEA showed that genes that were upregulated in breast tumors with high ATL2-2 mRNA levels correlated with genes in the Hallmark pathways E2F targets, MYC targets, and G2M checkpoint." (PMID 37628611, 2023). "To test this idea, we overexpressed or reduced KLF8 expression in MDA-MB-231 and SUM159 cells and assessed mRNA and protein expression of major stem cell factors that are associated with breast tumor development and include OCT4, SOX2, NANOG and c-MYC." (PMID 37152043, 2023). "In effect, higher MYC expression has been reported in aggressive breast tumors and is a driver of epithelial-mesenchymal transition." (PMID 36352274, 2022). "G9a was also demonstrated to interact with MYC and suppress its target genes by favoring H3K9me2, in order to stimulate MYC-dependent breast tumor growth." (PMID 34685453, 2021).
breast tumors (continued). "A recent study analyzing over 2000 breast tumors highlighted the functional role of MYC in the context of TNBC." (PMID 33808259, 2021). "In this study, we reported that PRKD3 activated ERK1‐c‐MYC axis to promote the breast tumour growth." (PMID 31944568, 2020). "In breast tumor, MYC expression correlates positively with miR-203b-3p and miR-203a-3p but negatively with BCL2L1 expression, resulting in formation of a TF-FFL." (PMID 32102656, 2020). "Recent research shows that HN1 can promote the invasion of breast tumors by increasing the activity of MYC." (PMID 32700728, 2020). "In conclusion, this study has shown the value of MYC targets scores in predicting tumor aggressiveness in ER-positive/HER2-negative breast tumors." (PMID 33143224, 2020). "Amplification of c-MYC and activation of its downstream effectors are related with high metastatic ability, endocrine resistance and poor disease outcome in breast tumors." (PMID 33489906, 2020). "In the current study, we comprehensive investigated ATM, ATR and MYC expressions at the transcriptional levels (n = 1950) and at the protein level (n = 1650) breast tumours." (PMID 30746633, 2019). "Kaplan–Meier analyses demonstrate that breast tumors with high expression of both EGFR and MYC are likewise associated with decreased patient survival." (PMID 31839995, 2019). "The MYC gene locus is amplified in about 16% of all breast tumors and about one-third of breast tumors overexpress MYC mRNA1–3." (PMID 30728358, 2019). "MYC is a major oncogene in many cancers, including in BRCA1 breast tumours, where BRCA1 loss leads to overexpression of MYC contributing to tumourigenes." (PMID 30323900, 2018). "SLC7A5 protein expression was significantly expressed in breast tumours with high Ki67, and the upstream effector MYC (p < 0.001)." (PMID 29566741, 2018). "Another recent study measured MYC gene copy number in 94 breast tumors of all subtypes with semi-quantitative multiplex PCR." (PMID 29523126, 2018). "The inverse correlations observed between transcript levels of both studied genes in the present study and disease stage are in accordance with the parallel expression of CCAT2 and MYC expressions in breast tumors, which has been observed in a previous study." (PMID 28480695, 2017). "All these results demonstrated that KDM3A/JMJD1A regulates breast tumor transformation through directly binding MYC and PAX3 oncogenes and modulating their transcription." (PMID 27034728, 2016). "Since we confirmed the synthetic lethal effect of FBXW7 knockdown with MYCER activation in MCF10A-MYCER cells, next we elected to examine the correlation between expression of FBXW7 and MYC in various breast tumor subtypes." (PMID 25669969, 2015). "This is consistent with reports from TCGA identifying MYC amplification and high-expression in basal-like breast tumors, which tend to be hypomethylated." (PMID 25960768, 2015). "They showed that CDK inhibition effectively induced tumor regression, indicating that aggressive breast tumors with elevated MYC expression are uniquely sensitive to CDK inhibitors." (PMID 24591761, 2014). "Metabolically stable small-molecule inhibitors of MYC hold significant promise as new agents to treat some drug resistant breast tumors." (PMID 25339305, 2014). "In contrast, deletion of STK11 in MYC-driven breast tumor models significantly reduced the latency period for tumor development." (PMID 24280377, 2013).
breast tumors (continued). "By integrative functional genomics and molecular cell biological approaches, we showed the involvement of EGFR, RAS, PI3K / AKT, MYC, E2F signaling in the regulation of these selected 1q genes in breast tumors." (PMID 24147022, 2013). "Our previous study on the patterns of oncogenic pathway activity in human breast tumors demonstrated clear correlations between the interferon pathways as well as between MYC and RAS, which are consistent with the findings of many other studies." (PMID 21672245, 2011). "Furthermore, SRSF1 has been shown not only to contribute to MYC’s oncogenic activity but also to cooperate with MYC in malignant transformation, promoting the formation of more-aggressive breast tumors." (PMID 26490253, 2015). "GRN was positively correlated with an average of 42.9% of genes in STAT3 signatures but with an average of only 13.5% of genes in MYC signatures, supporting the preferential association of GRN expression with signatures indicative of functional STAT3 activation in primary breast tumors." (PMID 26000098, 2015). "MYC expression is increased in antiestrogen resistant breast tumors." (PMID 25339305, 2014). "We conclude that over-expression or constitutive activation of MYC, possibly in conjunction with elevated E2F activity, may contribute to increased proliferation in ER− breast tumors, particularly in the basal subgroup." (PMID 19270750, 2009). "Nevertheless, we speculate that the combined inactivation of both the MYC and K-Ras pathways in these breast tumor models will also result in complete tumor regression." (PMID 18461184, 2008). "However, high FBXO28 levels were also found to be associated with poor prognosis in particular patient subgroups, including low proliferative luminal A tumours and in highly proliferative (high Ki-67 levels), poorly differentiated breast tumours, presumably tumours with hyperactivation of MYC." (PMID 23776131, 2013). "This study aimed to examine how inhibiting miR-32-5p affected the behavior of breast tumor cells (MCF-7), particularly focusing on changes in cellular apoptosis and proliferation, and to investigate its relationship with c-MYC expression." (PMID 40711670, 2025). "In this direction, we investigated the expression of the MYC and OCT4 proteins in subpopulations of breast tumour cells." (PMID 35563449, 2022). "Differentiated CD44 tumour cells with MYC and OCT4 stem protein expression are present in breast tumours." (PMID 35563449, 2022). "While CNA events in deep or shallow depletion rarely or less occurred, EGFR, MYC, IRF2BP2, ASAP1, and CCT5 (except for DRD1) often underwent copy gain and amplification, acquiring CNA-driven expression in the breast tumors." (PMID 32235890, 2020). "Patient’s breast tumour and bone metastasis-derived PDX show amplification of FGFR1, MYC, CCNE2, CCND1 and AURKA." (PMID 32792481, 2020). "We next sought to address the correlation between CNA frequencies and expression levels of MYC, EGFR, ASAP1, IRF2BP2, CCT5, and DRD1 in broad BC cell lines and breast tumors and the clinical relevance of the genes to patients with BC." (PMID 32235890, 2020). "Using candidate-gene approach, we examined the promoter methylation level of AR, ESR1, hTERT, MYC, RASSF1 and WNT1 in 69 male breast tumors and corresponding blood samples, 7 normal breast tissues and 8 normal lymph node samples." (PMID 29731982, 2018). "In particular, we examined promoter methylation status of genes involved in signal transduction and hormone signalling, including AR, ESR1, hTERT, MYC, RASSF1 and WNT in male breast tumors, paired blood samples and normal tissues." (PMID 29731982, 2018). "Also, studies evaluating differences in MYC amplification between primary breast tumors and metastatic sites in bone, lung, and brain would be useful to determine whether lethality of metastatic disease is related to MYC amplification, especially in minority populations." (PMID 29523126, 2018).